PVT1 (Pvt1 oncogene)
Synonyms: NCRNA00079; LINC00079; onco-lncRNA-100; MIR1204HG; TP53LC09
Gene: Long non-coding RNA gene on chromosome 8 (127,794,513 to 128,188,202, forward strand). Ensembl gene ENSG00000249859.
Gene Ontology:
Molecular function: miRNA binding; miRNA inhibitor activity via base-pairing; pre-mRNA 5'-splice site binding
Biological process: lncRNA-mediated post-transcriptional gene silencing; positive regulation of gene expression; positive regulation of miRNA catabolic process; miRNA-mediated post-transcriptional gene silencing; mRNA 5'-splice site recognition
Cellular component: RISC complex; U1 snRNP
Diseases named in the same sentence as PVT1 in open-access papers:
PVT1 is named in the same sentence as 281 diseases in open-access papers, as found by Europe PMC text mining. Sharing a sentence is not in itself a finding about the gene and the disease. The quoted sentences say what the papers report.
gastric cancer (143 papers, 2015 to 2025). A primary or metastatic malignant neoplasm involving the stomach. "Plasmacytoma variant translocation 1 (PVT1) is another lncRNA involved in VM formation in gastric cancer." (PMID 40277941, 2025). "PVT1 has been linked to a variety of cancers, including gastric cancer, breast cancer, ovarian cancer, and skin cancer." (PMID 38792557, 2024). "Numerous studies have reported that the over-expression of PVT1 is implicated in the development of different cancer types such as gastric cancer, colorectal cancer, non-small cell lung cancer, ovarian and breast cancer." (PMID 36624401, 2023). "LncRNA PVT1 has been shown to promote cell proliferation through epigenetic regulation of p15 and p16 and is associated with poor prognosis in gastric cancer." (PMID 35592755, 2022). "PVT1 is an oncogenic lncRNA and is associated with many cancer types including colorectal and gastric cancers." (PMID 34336125, 2021). "The abnormal expression of lncRNA PVT1 is associated with many human tumors, such as lung cancer, gastric cancer, colorectal cancer, breast cancer, pancreatic cancer, and prostate cancer." (PMID 34900027, 2021). "In this review, we discuss the mechanisms of action underlying PVT1 oncogenic role in colorectal and gastric cancer such as MYC upregulation, miRNA production, competitive endogenous RNA (ceRNA) function, protein stabilization, and epigenetic regulation." (PMID 32083000, 2020). "LncRNA plasmacytoma variant translocation 1 (PVT1) promotes gastric cancer cell proliferation by targeting the occupancy of EZH2 within the PRC2 complex to epigenetically regulate p15 and p16." (PMID 32429086, 2020). "The lncRNA plasmacytoma variant translocation 1 (PVT1) is highly expressed in gastric cancer tissues of cisplatin-resistant patients and cisplatin-resistant cells." (PMID 32164712, 2020). "PVT1 Sv-214 specific evaluation in gastric cancer patients was associated with larger tumor size (5 cm cut off), advanced stage (III-IV) and reduced overall survival." (PMID 32083000, 2020). "Plasmacytoma variant translocation 1 (PVT1) is a long noncoding RNA encoded by the human PVT1 gene, which has been verified to mediate tumorigenesis in gastric cancer." (PMID 31205469, 2019). "Upregulated PVT1 in gastric cancer can promote the proliferation and invasion of gastric cancer cells, which is associated with poor prognosis." (PMID 31309249, 2019). "The expression of PVT1 is upregulated in gastric cancer tissues and significantly associated with advanced tumor and lymph node metastasis." (PMID 31309249, 2019). "PVT1 has been implicated in several cancer types including gastric cancer, ovarian cancer and breast cancer." (PMID 30217017, 2018). "Subgroup analysis indicated that there was a significant association between PVT1 overexpression and poor OS of patients with gastric cancer, gynecology cancer and lung cancer." (PMID 29348896, 2017). "A significant association was found between distant metastases and PVT1 in gastric cancer (OR = 2.69, 95%CI: 1.23–5.86) and lung cancer (OR = 8.65, 95% CI 3.15–23.73)." (PMID 29348896, 2017). "The study suggested that PVT1 may act as a pro‐inflammatory factor and regulate gastric cancer caused by HP infection." (PMID 40778107, 2025). "LncRNA PVT1 is encoded by the human PVT1 gene and is involved in the development of a variety of tumors, such as gallbladder cancer, colorectal cancer, gastric cancer, lung cancer, thyroid carcinoma, breast cancer, nasopharyngeal carcinoma, and pancreatic cancer." (PMID 32156248, 2021). "Moreover, in gastric cancer (GC), higher PVT1 expression is significantly associated with greater infiltration depth and advanced TNM stage based on tissues and cell lines, as well as in animal experiments than in normal." (PMID 35071016, 2021). "Similarly, in gastric cancer, elevated PVT1 expression was found to be associated with high tumor stage (III–IV), lymph node metastasis and overall/disease-free survival." (PMID 32083000, 2020).
gastric cancer (continued). "The aberration of PVT1 is associated with an increased copy number, upregulation, or over expression of PVT1 in different malignancies including cervical cancer, bladder cancer, colorectal cancer, gastric cancer, hepatocellular carcinoma, and lung cancer." (PMID 31877167, 2019). "Upregulation of PVT1 in gastric cancer was also associated with inhibition of miR-186 function." (PMID 29147648, 2017). "Downregulation of miR-152 in gastric cancer could be also caused by PVT1 (plasmacytoma variant translocation 1), an oncogenic lncRNA that acts as a precursor of six miRNAs (i.e., miR-1204, miR-1205, miR-1206, miR-1207-5p, miR-1207-3p, and miR-1208)." (PMID 29147648, 2017). "In the present study, we also evaluated the association between distant metastases and PVT1 expression for 8 studies including 878 patients with four different cancers, including gastric cancer (n = 4), lung cancer (n = 2), colorectal cancer (n = 1) and esophageal cancer (n = 1)." (PMID 29348896, 2017). "The plasmacytoma variant translocation 1 gene (PVT1) has been demonstrated as an oncogenic lncRNA in multiple cancers, including ovarian cancer, breast cancer, prostate cancer, cervical cancer, gastric cancer and non-small cell lung cancer." (PMID 29244840, 2017). "Moreover, PVT1 promoted proliferation and was associated with a poor prognosis in gastric cancer, and PVT-1 resulted in a poor prognosis by inhibiting apoptosis of colorectal cancers." (PMID 27813492, 2016). "Long non-coding RNA plasmacytoma variant translocation 1 (PVT1) has been reported to be a vital modulator in tumorigenesis of gastric cancer (GC)." (PMID 36760720, 2023). "Among them, plasma tumor variant translocation 1 (PVT1) was reported as a key biomarker of prognosis for patients with gastric cancer (GC)." (PMID 34900027, 2021). "In silico analysis identified PVT1 Sv-214 as ceRNA for miR-128, and the initial observation was confirmed experimentally in colorectal cancer cell lines through gain and loss-of-function experiments against PVT1 Sv-214 isoform and further extended to gastric cancer cell line model." (PMID 32083000, 2020). "To analyze the level and diagnostic value of plasmacytoma variant translocation 1 (PVT1) in gastric cancer (GC) of Han and Uygur in Xinjiang, China, we collected 42 GC and 47 normal gastric tissues and performed tissue microarray." (PMID 30679629, 2019). "Similarly, in gastric cancer, high PVT1 expression is always associated with a poor prognosis." (PMID 31205469, 2019). "Similarly, in cisplatin and 5-fluorouracil-resistant gastric cancer patients the expression of lncRNA plasmacytoma variant translocation 1 (PVT-1) and lncRNA ANRIL (antisense to CDKN2B locus) are also increased and these non-coding RNAs promote MDR1 upregulation and drug resistance." (PMID 29967761, 2018). "Furthermore, 12 studies comprising 1173 patients were pooled to evaluate the association between lymph node metastases and PVT1 expression in different cancers, such as gastric cancer (n = 5), lung cancer (n = 4), colorectal cancer (n = 1), pancreatic cancer (n = 1) and bladder cancer (n = 1)." (PMID 29348896, 2017). "Further studies revealed that knockdown of circ-PVT1 promoted apoptosis and reduced invasion and autophagy by negatively targeting miR-30a-5p, thus inhibiting cisplatin resistance in resistant gastric cancer cells." (PMID 40936702, 2025). "Knockdown of PVT1 in gastric cancer cells led to the inhibition of inflammatory cytokines such as tumour necrosis factor‐α (TNF‐α), interleukin (IL)‐1β, IL‐6 and IL‐8." (PMID 40778107, 2025). "In summary, PVT1 plays a pivotal role by promoting EMT and VM formation in gastric cancer through the PVT1/STAT3/Slug axis." (PMID 40277941, 2025). "Circ-0006528 regulates paclitaxel resistance in breast cancer, and circ-PVT1 can enhance PTX resistance of gastric cancer cells." (PMID 38733530, 2024).
gastric cancer (continued). "Recent research has demonstrated that the gastric cancer cell viability and proliferation rate decreased, and the expression of long non-coding RNA (lncRNA) PVT1 was significantly reduced after culturing in a medium lacking Met." (PMID 38397398, 2024). "For instance, in gastric cancer cells, increased levels of circAKT3 have been linked to reduced sensitivity to cisplatin in gastric cancer cells, while circ‐PVT1 has the potential to enhance resistance against paclitaxel in gastric cancer cells." (PMID 39347936, 2024). "PVT1 is an oncogenic lncRNA that is significantly expressed in gastric cancer, especially in patients with low differentiation and progressive stages." (PMID 37602326, 2023). "A previous study has reported that the increased expression of PVT1 was associated with enhanced invasion of gastric cancer cells to lymph nodes; they suggested PVT1 as a new biomarker and therapeutic target for gastric cancer." (PMID 36624401, 2023). "Correlation of PVT1 expression and clinical prognosis in gastric cancer regarding various clinicopathological factors." (PMID 37255541, 2023). "PVT1 has been reported to have obvious cancer-promoting effects in gastric cancer, colorectal cancer, pancreatic cancer and breast cancer." (PMID 36941464, 2023). "LASSO Cox regression with 10-fold cross-validation for the clinical prognostic effect of gastric cancer identified one lncRNA (PVT1), one miRNA (hsa-miR-130a-3p) and one mRNA (RECK)." (PMID 37255541, 2023). "PVT1 improves the migration of gastric cancer cells by competing for binding with miR-30a and influencing the expression of Snail." (PMID 37255541, 2023). "LncRNA PVT1 has been identified in gastric juices and is believed to be a prognostic biomarker of gastric cancer." (PMID 37255541, 2023). "The activation of the STAT3/VEGFA signaling axis by lncRNA PVT1 has been found to enhance angiogenesis in gastric cancer." (PMID 37915049, 2023). "Our findings in line with the prognostic role of PVT1 in colon cancer, gastric cancer and melanoma cancer." (PMID 37202742, 2023). "Du and colleagues found that PVT1 can modulate the expression of anti-apoptotic Bcl2 and increase 5-FU resistance in gastric cancer." (PMID 37104009, 2023). "The researchers also showed that, in gastric cancer, PVT1 increases 5-FU resistance by activating Bcl-2, which in turn inhibits apoptosis." (PMID 37104009, 2023). "For example, the expression of circAKT3 is high in cisplatin-resistant gastric cancer cells, and circ-PVT1 can promote the paclitaxel resistance of gastric cancer cells." (PMID 35508967, 2022). "For example, PVT1 was reported to promote tumorigenesis in nonsmall cell lung cancer and multidrug resistance in gastric cancer." (PMID 36101743, 2022). "Circular PVT1 was first identified as a senescence suppressor and then as a proliferative factor in gastric cancer." (PMID 35090471, 2022). "In gastric cancer, for example, circ-PVT1 is upregulated and sequesters miR-124-3p, thereby upregulating ZEB1 expression and promoting tumor cell resistance to paclitaxel treatment." (PMID 35974419, 2022). "For example, PVT1 stimulated angiogenesis by triggering the STAT3/VEGFA signaling pathways in gastric cancer." (PMID 35813862, 2022). "In gastric cancer cells, PVT1 was describes as acting as a sponge of miRNA-152, upregulating fibroblast growth factor 2 (FGF2), as in one of our proposed ceRNA axes." (PMID 35328496, 2022). "Circular PVT1 was found upregulated in gastric cancer and correlated with tumor progression and poor prognosis." (PMID 35090471, 2022). "In gastric cancer cells, PVT1 interacts with STAT3 and protects STAT3 from poly-ubiquitination and proteasome-dependent degradation to sustain the stability of p-STA3." (PMID 36295083, 2022).
gastric cancer (continued). "A comprehensive literature searching was performed in PubMed, Cochrane Library, Web of Science, Embase, CNKI, CBM, and Wanfang Database to identify published studies on the expression level of lncRNA PVT1 in human gastric cancer." (PMID 34900027, 2021). "lncRNA PVT1 has been studied in multiple cancer types, including gastric cancer, ovarian cancer, and pancreatic cancer." (PMID 34805417, 2021). "In the related studies on liver cancer, lung cancer, gastric cancer, and prostate cancer, abnormal circ_PVT1 affects the metabolism, metastasis, and immunity of tumor cells." (PMID 34336825, 2021). "Niu et al20 demonstrated that gastric cancer tissues exhibit significantly enhanced expression of lncRNA PVT1 and that lncRNA PVT1 can regulate the invasion and proliferation of gastric cancer cells via targeted regulation of miR‐125 activity." (PMID 32960485, 2021). "A previous study indicated that PVT1 was linked to the activation of STAT3/VEGFA signaling and promoted angiogenesis in patients with gastric cancer." (PMID 34336125, 2021). "It has been found that circular PVT1 is a carcinogenic non-coding RNA and has important clinical significance in numerous carcinoma including ovarian cancer, gastric cancer and thyroid cancer 33-42." (PMID 33391456, 2021). "The authors likened PVT1 to a “sponge” in gastric cancer to inhibit miR-152, and made it an emerging potential therapeutic target for gastric cancer." (PMID 34222025, 2021). "Numerous studies have reported that PVT1 showed higher expression in gastric cancer tissues and cell lines, can promote the proliferation and invasion of GC cells, and is closely related to advanced tumor stage and lymph node metastasis." (PMID 34900027, 2021). "This is in agreement with previous studies reporting significant expression of PVT-1 in gastric cancer and cervical cancer." (PMID 33670447, 2021). "Previous studies have shown that PVT1 is upregulated in poorly differentiated and advanced gastric cancer patients, and high- PVT1 levels predict shorter survival times, suggesting its potential diagnostic and prognostic value." (PMID 34876056, 2021). "It is reported that PVT1 was highly expressed in gastric cancer (GC) tissues, and high PVT1 level was correlated with tumor stage, lymph node metastasis, and poor prognosis." (PMID 34179148, 2021). "The lncRNA PVT1 also promotes gastric cancer migration by acting as a ceRNA for miR-30a and regulating snails." (PMID 34101736, 2021). "PVT1 was also reported to be related to cisplatin sensitivity in colorectal cancer and 5FU resistance in gastric cancer." (PMID 32727463, 2020). "Simultaneously, several studies had shown that PVT1 is upregulated in various human tumors including gastric cancer 19, hepatic carcinoma 20, and prostate cancer." (PMID 31897242, 2020). "PVT1 expression in stomach cancer is directly regulated by FOXM1 (Forkhead Box M1) transcription factor." (PMID 32083000, 2020). "Several research groups have demonstrated the overall ability of PVT1 to sustain in vitro and in vivo cell growth, clonogenicity, migration, and invasion, both in colorectal and gastric cancer epithelial cells." (PMID 32083000, 2020). "EZH2 forms a molecular complex with PVT1 to function as an repressive driver of p15 and p16 in gastric cancer." (PMID 31320749, 2020). "Previous studies have revealed that the KAT family protein KAT2A can bind to the lncRNAs GClnc1 and PVT1 in gastric cancer and NPC, respectively." (PMID 33330099, 2020). "PVT1 transcript levels changes upon manipulation of FOXM1 protein expression in gastric cancer cells." (PMID 32083000, 2020). "For example, lncRNA PVT1 serves as a ceRNA in gastric cancer to sponge miR-186, thus promoting proliferative and invasive rates of gastric cancer cells." (PMID 32047553, 2020). "The role of PVT1 in cisplatin resistance gastric cancer was explored by examining the effects of PVT1 on the expression of some genes associated with drug resistance." (PMID 32117705, 2020).